GZMK (granzyme K)
Diseases named in the same sentence as GZMK in open-access papers (continued):
Sharing a sentence is not in itself a finding about the gene and the disease.
breast carcinoma (7 papers, 2022 to 2025). "A robust association between GZMK expression and T cell presence was noted in the breast cancer tumor microenvironment (TME), with strong correlations with ESTIMATEScore (Cor = 0.743, P < 0.001), ImmuneScore (Cor = 0.802, P < 0.001), and StromalScore (Cor = 0.516, P < 0.001)." (PMID 38833021, 2024). "We focused primarily on analyzing the expression levels of GZMK in breast cancer tissues and normal tissues using TCGA data, as well as in five cell lines." (PMID 38833021, 2024). "Further laboratory-based research combined with clinical studies is necessary to validate these findings and to provide a more comprehensive understanding of GZMK's role in predicting prognosis and immunotherapy response in breast cancer patients." (PMID 38833021, 2024). "When analyzing the impact of GZMK on the survival of breast cancer patients, it was found that high expression of GZMK can improve patients' OS, PFS, RFS." (PMID 38833021, 2024). "This article discusses the expression difference of GZMK in breast cancer, its impact on survival, the correlation analysis with immune markers, and the prediction of the efficacy of tumor immunotherapy." (PMID 38833021, 2024). "Our study also reveals differential expression of GZMK in breast cancer, with higher expression levels noted in cancer tissues." (PMID 38833021, 2024). "In conclusion, our analysis of GZMK expression differences in breast cancer has provided initial insights into its potential mechanisms of action." (PMID 38833021, 2024). "A specific analysis of the impact of GZMK high and low expression groups on OS in the TCGA database revealed a total of 1070 cases of breast cancer patients, with 535 patients in each group." (PMID 38833021, 2024). "Significant differences in GZMK expression were observed among molecular subtypes of breast cancer (P < 0.05)." (PMID 38833021, 2024). "Analysis of clinical pathological features revealed significant correlations between GZMK expression and lymph node staging, differentiation grade, and molecular breast cancer subtypes." (PMID 38833021, 2024). "We utilized data from the TCGA and GEO databases and employed a range of analytical methods including GO, KEGG, GSEA, ssGSEA, and PPI to investigate the impact of GZMK on breast cancer." (PMID 38833021, 2024). "Among all breast cancer patients (n = 1,879), those in the high GZMK expression group (n = 935) had significantly better OS compared to those in the low expression group (n = 944), with statistical significance (HR = 0.58 [0.48–0.71], P < 0.001)." (PMID 38833021, 2024). "Although the apoptosis mechanisms mediated by GZMA and GZMB are well-documented, the roles of other granzymes, especially GZMK, which exhibits trypsin-like catalytic activity, are less understood in Tc-mediated cytotoxicity, particularly in breast cancer." (PMID 38833021, 2024). "Despite its importance, the specific role of GZMK in breast cancer and its mechanisms are not well understood." (PMID 38833021, 2024). "The strong linear correlation between GZMK and PD-1 in breast cancer suggests a potential influence on T-cell differentiation and the T-cell receptor signaling pathway, offering a new therapeutic target for further exploration in breast cancer immunotherapy." (PMID 38833021, 2024). "There is a significant correlation between GZMK and PD-1/PD-L1, providing new possibilities for mechanistic research in breast cancer immunotherapy." (PMID 38833021, 2024). "Elevated GZMK expression is associated with improved OS and RFS, suggesting its potential as a prognostic marker for breast cancer survival and as a predictor of the efficacy of immunotherapy." (PMID 38833021, 2024). "Although we have found that GZMK plays an important role in breast cancer and has significant value in predicting breast cancer prognosis, it holds promise as a target for breast cancer immunotherapy or as a biomarker for predicting immunotherapy efficacy." (PMID 38833021, 2024).
breast carcinoma (continued). "GZMK's role in the tumor microenvironment (TME) of breast cancer was assessed based on the eight most common algorithms (CIBERSORT, CIBERSORT ABS, EPIC, ESTIMATE, MCP-counter, Quantiseq, TIMER, and xCell)." (PMID 38833021, 2024). "We also found a strong linear correlation between GZMK and PD-1 in breast cancer, providing a new therapeutic target for further exploration of breast cancer immunotherapy, especially in triple-negative breast cancer." (PMID 38833021, 2024). "In all breast cancer patients (n = 1879 cases), the high expression group of GZMK (n = 935 cases) had better OS than the low expression group (n = 944 cases), with statistical significance (HR = 0.58 (0.48–0.71), P < 0.001)." (PMID 38833021, 2024). "Our study provides insights into the differential expression of GZMK in breast cancer and its potential mechanisms in breast cancer pathogenesis." (PMID 38833021, 2024). "Moreover, GZMK expression was found to be significantly correlated with survival rates in breast cancer in another study." (PMID 40002821, 2025). "We found that SLAMF6 expression was highly correlated not only with the expression of T-cell markers (CD3E, CD8B, CD8A, and CD4) but also with upregulation of TCF7, PDCD1 encoding PD-1, GZMK, and effector-associated genes including IFNG and PRF1 in breast cancer." (PMID 38287061, 2024). "A multifactorial COX regression analysis was performed to assess the impact of clinical-pathological indicators (age, pathological T stage, N stage, M stage, overall stage, and molecular subtype) and GZMK expression levels on the OS of breast cancer patients in the TCGA database." (PMID 38833021, 2024). "This suggests that GZMK-positive breast cancer may benefit more from anti-PD-1/PD-L1 immunotherapy, indicating that GZMK could be a target for predicting the efficacy of immunotherapy in breast cancer." (PMID 38833021, 2024). "One study reported ZNF331 expression in T cell clusters in breast cancer with resident effector memory phenotype co-expressing regulatory elements that may involve in cell cycle regulation and upregulating GZMK over GZMB and PRF1, aligning with our observations." (PMID 40028342, 2025). "Therefore, further research into the molecular mechanisms of granzyme-induced apoptosis, especially the role of GZMK in breast cancer, is crucial for advancing our understanding of breast cancer immunotherapy and enhancing the reliability of clinical evidence for its treatment." (PMID 38833021, 2024). "Among all breast cancer patients (n = 4929), the RFS of the high GZMK expression group (n = 2464) was superior to that of the low expression group (n = 2465), with statistical significance (HR = 0.78 [0.71–0.87], P < 0.001)." (PMID 38833021, 2024). "High GZMK expression can improve OS and RFS in breast cancer patients, demonstrating its predictive value for patient survival and potential in predicting immunotherapy outcomes." (PMID 38833021, 2024). "In our analysis of GZMK and immune cell infiltration in the TME of breast cancer, we found a close relationship with T cells." (PMID 38833021, 2024). "In an analysis of the TCGA database, mRNA relative expression levels of GZMK (log2(TPM + 1)) were correlated with CTLA4, PD-1, PD-L1, CD48, and CCR7 in patients with breast cancer." (PMID 38833021, 2024). "Overall, kidney and breast cancers displayed the highest expression of GZMA, GZMB, GZMK and PRF1." (PMID 40002821, 2025). "Subgroup analysis across different breast cancer subtypes showed that high GZMK expression improved OS in triple-negative breast cancer (TNBC) (n = 404), Luminal A (n = 794), Luminal B (n = 515), and HER2-positive breast cancer (n = 166), with statistically significant differences (P < 0.05)." (PMID 38833021, 2024). "Subgroup analysis revealed that GZMK expression levels were relatively higher in patients with ER-negative breast cancer, PR-negative breast cancer, and HER2-positive breast cancer." (PMID 38833021, 2024).
viral infections (7 papers, 2017 to 2026). "This research explores the structural and functional consequences of high-impact missense variants in three immune-related genes MMP8 (D253N, Y261S), GZMK (A42P, L122P), and OASL (W216C) with possible relevance to host response in epidemic viral infections." (PMID 41807577, 2026). "The induction of GZMK-expressing T effector memory cells has been observed in the initial stages of viral infections other than CMV, such as SARS-CoV-2 and influenza virus." (PMID 40343282, 2025). "This may in part reflect a sensitivity issue, as increases in circulating granzyme K levels after viral infections can be substantially more modest than those seen for granzyme A." (PMID 28207896, 2017). "Furthermore, mice lacking GzmK appear totally healthy, resist viral infection, and have no defect in killing in vivo or in vitro." (PMID 35881628, 2022).
autoimmune disease (6 papers, 2015 to 2025). A disorder resulting from loss of function or tissue destruction of an organ or multiple organs, arising from humoral or cellular immune responses of the individual to their own tissue constituents. "GZMK has been implicated in the pathogenesis of autoimmune diseases, including RA and OA." (PMID 41291399, 2025). "Cytotoxic CD8 T cells, including PRF1 + and GZMK + cells, are known to be involved in the pathogenesis of autoimmune diseases and viral myocarditis." (PMID 41510228, 2025). "Accordingly, CD8+GZMK+ and CD4+GZMK+ T cells are enriched at sites of chronic inflammation in the context of autoimmune diseases and tumors likely contributing to chronicity, tumor immune escape, outgrowth and metastasis." (PMID 41030456, 2025). "We further demonstrated that patients in group G2 had a concomitant enrichment in paired kidney samples of granzyme B+ and granzyme K+ T cell subsets, a major driver of tissue inflammation in autoimmune diseases that correlates with an extrafollicular B cell response in LN kidneys." (PMID 40536813, 2025).
lung carcinoma (5 papers, 2022 to 2023). "As reported, pre-exhausted GZMK+ T subpopulation were regarded as pre-activated T cells which would accumulate in responsive lung cancer and melanoma tumors following immune-checkpoint-based treatment." (PMID 37488416, 2023). "The fractions of CD8+ T cells in two lung cancer subtypes were comparable with that in each other, but the Effector cells were enriched in LUAD, and cytotoxic, exhausted, GZMK+ Effector as well as KLRC1+ Effector cells were abundant in LUSC." (PMID 36008393, 2022).
psoriasis (5 papers, 2010 to 2025). An autoimmune condition characterized by red, well-delineated plaques with silvery scales that are usually on the extensor surfaces and scalp. "The contribution of GzmK to epidermal hyperplasia, a hallmark of psoriasis, was assessed in the murine model of IMQ-induced psoriasis-like skin inflammation." (PMID 38903528, 2024). "Altogether, these results indicate that GzmK deficiency attenuates disease severity in the murine model of IMQ-induced psoriasis." (PMID 38903528, 2024). "In an established murine model of imiquimod (IMQ)-induced psoriasis, genetic loss of GzmK significantly reduced disease severity, as determined by delayed plaque formation, decreased erythema and desquamation, reduced epidermal thickness, and inflammatory infiltrate." (PMID 38903528, 2024). "Separately, in oxazolone-dermatitis and imiquimod-psoriasis models of inflammatory skin disease, severity is reduced in GzmK-/- mice." (PMID 40607408, 2025). "In the psoriasis mice, GzmK-/- mice have reduced plaque formation, less erythema, and decreased epidermal thickening." (PMID 40607408, 2025). "Tc17 cells were expanded in psoriasis while cytotoxic CD8 T cells (GZMB or GZMK high) were expanded in DM, CLE and vitiligo (scCODA FDR < 0.01)." (PMID 40894544, 2025). "In contrast to GzmK KO mice, infiltration of macrophages (F4/80+) (CD11c+), two major sources of IL-23 in psoriasis, were observed in IMQ-treated WT mice." (PMID 38903528, 2024). "Despite the presence of GzmK-positive mast cells in both healthy and psoriatic skin, their potential contribution to the development of psoriasis warrants further investigation." (PMID 38903528, 2024). "In the current study, GzmK levels were significantly increased in skin lesions from human psoriasis patients, predominantly within the dermal inflammatory cell infiltrate." (PMID 38903528, 2024). "In all stained psoriasis lesions, GzmK-positive cells were primarily located within the inflammatory cell infiltrate of the papillary dermis and adjacent to small blood vessels." (PMID 38903528, 2024). "Within psoriasis lesions, GzmK-positivity was also observed in the extracellular milieu surrounding the GzmK-positive cells compared with healthy controls, indicating potential extracellular secretion." (PMID 38903528, 2024). "Serial immunostaining and co-immunofluorescence of human psoriasis lesions further revealed a population of CD68+ cells (monocytes/macrophages) positive for GzmK." (PMID 38903528, 2024). "According to this search, the majority of prioritized datasets were related to psoriasis, underscoring the significance of GzmK to psoriasis pathology." (PMID 38903528, 2024). "In agreement with the GzmK mRNA expression data, all psoriasis skin samples exhibited a significant increase in GzmK protein levels compared with healthy control skin." (PMID 38903528, 2024). "Using the established murine model of imiquimod (IMQ)-induced psoriasis-like skin inflammation, a psoriasis-like phenotype was induced in both wild-type (WT) and GzmK KO mice." (PMID 38903528, 2024). "GzmK contributed to disease severity in the murine model of IMQ-induced psoriasis, as reflected in earlier clinical disease with more severe erythema and desquamation in WT mice compared to GzmK KO mice." (PMID 38903528, 2024). "Macrophages were identified as the largest population of GzmK-positive cells present exclusively within psoriasis lesions." (PMID 38903528, 2024). "The emerging pro-inflammatory effects of the serine protease, GzmK, initially prompted us to explore its potential role in psoriasis pathogenesis." (PMID 38903528, 2024). "Although the proportion of GzmK-positive mast cells in psoriatic lesions does not significantly differ from that in healthy skin, this does not rule out a pathogenic role in psoriasis." (PMID 38903528, 2024).
psoriasis (continued). "In comparative sequence analysis, human and mouse GzmK exhibited a 71.82% amino-acid sequence identity and full conservation of the catalytic triad (His, Asp, Ser), underscoring the relevance of the mouse model for investigating the mechanistic role of GzmK in the context of psoriasis." (PMID 38903528, 2024). "Importantly, dataset enrichment analysis revealed ‘psoriasis’ as the disease category with the highest number of relevant datasets retrieved, further emphasizing its significance in the context of GzmK." (PMID 38903528, 2024). "The present study suggests that there may be multiple cell sources that contribute to elevated GzmK that is observed in psoriasis lesions." (PMID 38903528, 2024). "A schematic overview depicting the role of GzmK in psoriasis can be seen in the Graphical Abstract." (PMID 38903528, 2024). "Provided the role of GzmK in selectively inducing IL-23p19, it could be a potential therapeutic target for psoriasis treatment." (PMID 38903528, 2024). "Taken together, we hypothesized that GzmK contributes to inflammation and/or keratinocyte proliferation in psoriasis." (PMID 38903528, 2024). "In this case, free GzmK may be accumulating and show upregulated activity in lesional psoriasis skin." (PMID 38903528, 2024). "Hence, GzmK produced and secreted by inflammatory macrophages may contribute to early psoriasis development." (PMID 38903528, 2024). "Consequently, GzmK may contribute to psoriasis epidermal hyperplasia through the stimulation of keratinocyte proliferation." (PMID 38903528, 2024). "The distribution of these cell lineages varied markedly between psoriatic and normal tissues, with an increased proportion of cycling keratinocytes, GZMK+ CD8 T cells, macrophages, and Treg cells observed in psoriasis samples." (PMID 40678620, 2025). "The functional role of GzmK in psoriasis was studied in WT and GzmK KO mice using the established IMQ model of psoriasis-like skin inflammation." (PMID 38903528, 2024). "Of particular relevance to clinically approved biologics, GzmK depletion in GzmK KO mice reduced the levels of both IL-17 and IL-23 in IMQ-induced psoriasis-like lesional skin." (PMID 38903528, 2024). "In psoriasis, CCL4, GZMK and KLRF1 show significantly higher, while ADM, ANXA3, IL4, MMP9 and OLR1 show significantly lower expression levels in patients with arthritis negative psoriasis compared to patients with symptoms of arthritis." (PMID 20444268, 2010). "In the present study, human psoriasis lesions exhibited elevated GzmK levels compared to non-lesional psoriasis and healthy control skin." (PMID 38903528, 2024). "Examples include PTGS2 in psoriasis; PTPN22 in RA and GZMK in IBD." (PMID 20444268, 2010). "Most notably, CLE and DM lesions were enriched for Th1-skewed CD4+ T cells that, unlike their counterparts in vitiligo, expressed cytotoxic effector molecules including GZMB, GZMK, and PRF1, a population nearly absent in healthy and psoriasis skin (scCODA FDR < 0.1)." (PMID 40894544, 2025). "No GzmK was detected in CD56+ (natural killer cells), CD1a+ (Langerhans cells), nor CD11c+ cells (dermal dendritic cells) despite each of these cell populations being elevated in human psoriasis lesions." (PMID 38903528, 2024).
Arthritis (4 papers, 2010 to 2025). Inflammation of a joint. "Moreover, in arthritis and dermatitis mice, GzmK-mediated complement activation reportedly contributes to disease progression." (PMID 40607408, 2025). "GzmK-/- mice display reduced arthritis severity and dermatitis with reduced complement activation." (PMID 40607408, 2025).
asthma (4 papers, 2021 to 2025). "Tissue GzmK levels predict chronic rhinosinusitis-associated nasal polyp recurrence and asthma comorbidity." (PMID 40607408, 2025). "In mouse asthma models, GzmK knockdown or pharmacological inhibition decreased tissue pathology and restored lung function." (PMID 40607408, 2025). "These GzmK+CD8+T cells in the lungs further exacerbate the inflammatory symptoms of asthma via their GzmK-dependent proteolytic functions and CS activation, which was restored in animals treated with anti-GzmK drugs or not seen in GzmK KO mice subjected to asthma." (PMID 41009359, 2025).
atherosclerosis (4 papers, 2022 to 2024). A disease characterized by the build-up of fatty material and calcium deposition in the arterial wall resulting in partial or complete occlusion of the arterial lumen. "With aging, the emergence of maladaptive T and B cells (e.g., CD4+CD28− and CD8+ Granzyme K (GzmK)+ T cells, and age-associated B cells) has also been observed in atherosclerosis." (PMID 39200181, 2024). "In both PSA and atherosclerosis CD8+ C3 T cells, expression profiles displayed a similar phenotype with high expression of T cell effector genes—for example, CCL5, GZMH, GZMA, GZMK and NKG7." (PMID 38665903, 2023).
Colorectal Tumor (4 papers, 2021 to 2024). "Moreover, it has been proven that GZMKhigh CD8+ T effector memory cells, a cell subset that is particularly similar to GZMK+ NK cells, were associated with poor clinical outcomes in patients with colorectal tumors." (PMID 39387546, 2024). "GZMK protein has been detected in human colorectal tumor tissues, showing a positive correlation with sVEGFR1 protein levels and a negative correlation with tumor angiogenesis and size in T4-stage tumors." (PMID 38833021, 2024).